EGFR (epidermal growth factor receptor)
Diseases named in the same sentence as EGFR in open-access papers (continued):
Sharing a sentence is not in itself a finding about the gene and the disease.
tumor (continued). "In all other cases, the primary tumour was positive for EGFR expression, whereas the metastatic lesion had lost EGFR expression." (PMID 25663927, 2015). "In our experimental regimen we were unable to induce a normalization window following treatment with erlotinib, the EGFR inhibitor, at 50 μg/kg, a dose that inhibits tumor growth by approximately 28%." (PMID 25758612, 2015). "Taken together, our data suggest that cetuximab can skew naïve monocytes toward an M1-polarized phenotype when co-cultured with EGFR+ tumor cells, including upregulation of M1 surface markers and cytokines and reduced M2 characteristics." (PMID 26579227, 2015). "Previous studies found that selective inhibitors of ADAM17 protease can block the tumor cell EGFR pathway." (PMID 25351873, 2015). "We previously identified SP as a key modulator of the steady state of HER2 and EGFR, with the functional consequence of enhanced tumor aggressiveness and tumor progression, and alterations in the cellular responses to apoptotic stimuli." (PMID 26114632, 2015). "Although oncogenic mutations in KRAS and EGFR occur in a significant fraction of human LUAD, they are rarely—if ever—observed together in the same tumor." (PMID 26047463, 2015). "All three lesions contained the original activating EGFR mutation, and the diaphragmatic NSCLC tumour harboured the EGFR resistance mutation, T790M, whereas the SCLCs did not." (PMID 25758528, 2015). "Our data suggest that the anti-tumor activity of this combination therapy involves the reduced expression of EGFR, Ki-67 and CD31, therefore demonstrating anti-proliferative and anti-antiangiogenic effects with low toxicity." (PMID 25918252, 2015). "Patients with non-small-cell lung cancer (NSCLC) develop acquired resistance to epidermal growth factor receptor tyrosine kinase inhibitors (EGFR TKIs) after tumor regression." (PMID 26172562, 2015). "The over-expression of EGFR and TGFα by neoplasias confers a more aggressive phenotype by inducing cancer metastasis, resistance to chemotherapy and poor prognosis." (PMID 25629807, 2015). "Consistently, p-ERK1/2, a known downstream effector of EGFR signalling, was higher in mPGES-1SC than mPGES-1KD tumours, suggesting that EGFR signalling plays a role in mPGES-1 enhancement of tumour growth." (PMID 26113609, 2015). "The multiplexed SCODA mutation detection assay was used to analyze extracted DNA from patient tumor tissue and pre-operative plasma samples for the presence of mutations in KRAS, PIK3CA, BRAF and EGFR as defined in our panel." (PMID 25575824, 2015). "The activity of c-Src tyrosine kinase interacts with receptor of tyrosine kinases such as EGFR in promoting tumor growth." (PMID 26617519, 2015). "PTEN was originally identified as a tumor suppressor gene, and miRNAs were known to be involved in the EGFR/PTEN/AKT pathway." (PMID 26170125, 2015). "To test the physiological significance of SOX2 induction following withdrawal ofmutant EGFR signaling, we first made use of mouse tumor models." (PMID 25686219, 2015). "ZD6474 is a small molecule inhibitor targeting multiple tyrosine kinases, including VEGFR-2 and EGFR), which can block multiple intracellular signaling pathways involved in tumor growth, progression, and angiogenesis in several tumors." (PMID 26050198, 2015). "The two signaling pathways are also the downstream signaling molecules of epidermal growth factor receptor (EGFR) signaling, which is mainly related with tumor occurrence and development." (PMID 26463718, 2015). "A total of 157 patients with diverse advanced cancers with known FFPE tumor tissue mutation status for mutations in at least one of the selected cancer genes, which included BRAF, EGFR, KRAS, PIK3CA, were enrolled." (PMID 25980577, 2015). "Taken together, these in vivo immunohistochemistry results were in agreement with our in vitro results and indicated that WB-308 suppressed NSCLC tumor growth by suppressing the EGFR signaling pathway." (PMID 25730907, 2015).
tumor (continued). "This association with poor prognosis is in accordance with the fact that nuclear EGFR activity was related to tumor radio and chemoresistance." (PMID 25784483, 2015). "We found that MCF10CA1a cells expressing mutant EGFR were the more aggressive compared to EV-control cells in the in vivo model of tumour formation." (PMID 25969993, 2015). "Recently, increased understanding of the molecular mechanism of tumor biology has led to the development of EGFR-targeting biomolecules, which exhibit improved target selectivity toward cancer cells." (PMID 25723471, 2015). "The SUVmax was significantly different according to the tumor grade, ER, EGFR, and Ki-67 for IDCs; however, only Ki-67 was significantly different for ILCs in the present study." (PMID 25889560, 2015). "We extended our analysis to include a number of tumour cell lines displaying increasing amounts of EGFR (HeLa, CASKI, BT20), compared with a normal fibroblast cell line (WI38)." (PMID 26264748, 2015). "It has been demonstratedthat tumours overexpressing both EGFR and c-Src have increased EGF-mediated DNAsynthesis, soft agar growth, increased phosphorylation of receptor-binding proteins(Shc, PLC-γ) and increased tumourigenesis in nude mice." (PMID 25658745, 2015). "The current study suggests that higher EGFR/MET ratios correlate with a tumor's addiction to the EGFR pathway." (PMID 26439803, 2015). "TG101348 was found to significantly increase the cytotoxicity of erlotinib, enhance erlotinib-induced apoptosis, and inhibit the tumor growth in EGFR-TTKI-resistant NSCLC cells." (PMID 25869210, 2015). "Several studies have shown that hypoxic regions within the tumor have an increased expression of EGFR compared to normoxic regions." (PMID 26032726, 2015). "Despite the anti-tumor effects of anti-EGFR-based therapies observed in many studies, gefitinib is clinically inactive in metastatic CRC23." (PMID 26542452, 2015). "Among IBC cases, 43 tissues were scorable for p-EGFR staining in the stroma and 40 for p-EGFR in tumor cells." (PMID 25887413, 2015). "This is in addition to the link we have shown between the ability of EGFR to undergo dimerization and the impact of gefitinib on tumor cell proliferation." (PMID 25762314, 2015). "One ADC tumor was positive for both EGFR and c-Met, and two tumors were positive for both c-Met and ROS1." (PMID 25989941, 2015). "The authors proposed that in tumour cells, TGFα-mediated EGFR activation induces EGFR/c-Met interaction, detectable as co-immunoprecipitation and resulting in increased c-Met phosphorylation and signalling." (PMID 28536399, 2015). "E-cadherin, p-EGFR and Ki-67 staining of specimens of primary tumor and metastases obtained from mice treated with erlotinib versus control were examined by immunohistochemistry." (PMID 25887413, 2015). "Human non small cell lung cancers (NSCLC) with activating mutations in the EGFR gene frequently experience significant tumor regression when treated with EGFR tyrosine kinase inhibitors (TKIs), although acquired resistance invariably develops." (PMID 26580964, 2015). "All amplified cases had high-level amplifications with ≥10 EGFR copies per tumor and showed large EGFR gene signal clusters." (PMID 25649416, 2015). "Since then, EGFR TKIs, such as gefitinib and the equally effective erlotinib, have become the first-line treatment option for NSCLC patients in which the tumor harbors activating EGFR mutations, based on the results of a number of phase III trials." (PMID 25591975, 2015).
tumor (continued). "Approximately 30% of all epithelial cancers have mutations, misregulations, or amplifications of EGFR or other family members, in fact EGFR participates in the tumor progression and invasion in TC, and it is overexpressed in ATC." (PMID 26635725, 2015). "To further examine the inhibitory effects of cetuximab plus saracatinib we evaluated this combination in vivo, in erlotinib-resistant, EGFR double mutant H1975 tumor xenografts." (PMID 26325669, 2015). "In the full cohort, intensity of p-EGFR staining in the tumor was higher in HER2-neu overexpressed tumors (P = 0.036, chi-squared statistic) however this association was not demonstrated in the IBC or non-IBC subsets perhaps owing to small numbers." (PMID 25887413, 2015). "The growth of the tumours induced by the MCF10CA1a cells was significantly increased by the expression of EGFR-DEL and to a lesser extent by EGFR-GS and EGFR-WT expression compared to the MCF10CA1a-EV cells." (PMID 25969993, 2015). "This protein is known to control tumor proliferation and acquisition of resistance by tumor cells towards EGFR inhibitors, therefore, development of a HER-3-targeted therapy is desirable." (PMID 26538233, 2015). "EGFR expression in tumor endothelial cells correlated with BTC expression in tumor cells, suggesting paracrine signaling." (PMID 26729094, 2015). "Owing to the overexpression of EGFR in many cancers, targeting EGFR is one of the effective strategies to suppress tumours in advanced stages." (PMID 26168967, 2015). "Given that the CXCL12/CXCR4 axis is considered to be a critical mediator of cancer–stroma interactions, our study also supports the important contributions of the tumor microenvironment to EGFR cross-talk with other signaling pathways in PDAC." (PMID 25679210, 2015). "SHH and increased EGFR expression are known to synergize and promote diverse events, including neural stem cell proliferation as well as tumor initiation and progression." (PMID 26158413, 2015). "Tumor samples from patients demonstrate correlation between stromal and tumor p-EGFR staining only in IBC tumors." (PMID 25887413, 2015). "This involvement of nuclear EGFR and DNA-PK enhancing DNA repair and cisplatin resistance was also demonstrated in human tumor cell lines." (PMID 25784483, 2015). "In GBM, the interplay between alternative RTK pathways can be exploited by tumor cells to enable the activation of oncogenes in the face of EGFR inhibition." (PMID 25885672, 2015). "The accuracy of our results was evaluated by a flow-cytometry analysis of the tumor cell lines to estimate the relative amounts of EGFR expression." (PMID 25716578, 2015). "In vivo, we used two xenograft mouse models, subcutaneous tumor growth and lung metastasis formation, of wild type EGFR NSCLC H322 and A549 cell lines, respectively." (PMID 26053020, 2015). "In this study, we also investigated EGFR mutation, KRAS mutation and ALK-IHC in the 14 patients with PPC whose tumor specimens were available." (PMID 26682906, 2015). "Luciferase signals were only observed in the MCF10CA1a-EGFR-DEL tumour-resected mice (2 out 5) but were lost after 6 months." (PMID 25969993, 2015). "Both RPTP-κ and PTPN2 knockdown increase levels of p-EGFR/Y1173 and of p-ERKs, indicating a tumor suppressor activity of these PTPs and/or a mitogenic function of EGFR/Y1173 phosphorylation." (PMID 26079946, 2015). "miR-7 has also been shown to inhibit proliferation in vitro and importantly, tumour growth in vivo, with regulation of EGFR commonly being attributed to this effect." (PMID 26308064, 2015). "Reduction of target phosphorylation was observed 1 hour after the administration of both the doses of the drug in tumor tissue expressing mutant EGFR." (PMID 26015408, 2015). "Based on these results, we anticipate that only HCC patients with EGFR-positive macrophages in their tumors would benefit from anti-EGFR therapies, while a worse outcome would be expected in patients where the EGFR is expressed in tumor cells." (PMID 26729094, 2015).
tumor (continued). "Although this tumor frequently overexpresses or possesses constitutively activated variants of IGF-IR and EGFR/Her-2, clinical trials using inhibitors of these receptors have failed." (PMID 25886138, 2015). "We have shown that preventing such feedback mechanism by inhibiting EGFR can effectively reduce tumor growth and prolong animal survival." (PMID 26023796, 2015). "Anti-EGFR therapeutic approaches, specifically receptor blocking monoclonal antibodies and small molecule tyrosine kinase inhibitors, prolong tumor stabilization." (PMID 25997612, 2015). "Potentially, miR-7 induces tumor suppressive actions by regulating not only EGFR but also the downstream signaling pathway at multiple sites." (PMID 26287249, 2015). "MiR-21 is an important oncogene; antisense inhibition of miR-21 induces cellular apoptosis in cooperation with EGFR-tyrosine kinase inhibitors and enhances sensitivity to radiotherapy and chemotherapy in a number of tumor contexts." (PMID 25788261, 2015). "We have shown that sulforaphane is a novel inhibitory modulator of EGFR expression and is effective in inhibiting the tumor growth of EGFR-TKI-resistant NSCLC cells." (PMID 26036303, 2015). "The traditional EGFR signaling pathway was detected by using samples obtained both in cells lines and xenograft tumor in mice." (PMID 26538117, 2015). "New mutations in RAS and PIK3CA emerged after therapy compared to archival tumour, and the emergence of multiple KRAS mutations in low levels after anti-EGFR therapy is a known resistance mechanism to anti-EGFR antibodies." (PMID 25889309, 2015). "Overexpression of EGFR is detected in various tumors and augmented activation of EGFR triggers multiple cellular effects that promote tumor progression." (PMID 25799278, 2015). "Our data show that, both in an isogenic model and in tumour cell lines, there is a progressive uncoupling of EGFR phosphorylation and ubiquitination at the supraphysiological EGFR level." (PMID 26264748, 2015). "Heterogeneity of GBM tumors with respect to in situ EGFR amplification was previously reported in tumor cells with EGFR amplification enriched at the invading margin of tumors." (PMID 25871395, 2015). "In our study we reveal an Erk2 dependent crosstalk between tumor stroma associated HGF/Met signaling and tumor cell associated EGFR signaling." (PMID 25884419, 2015). "This metaanalysis of transcriptional and metabolic differences between EGFR inhibitor-resistant vs. sensitive cell lines identifies changes that allow tumor cells to evade EGFR-inhibition." (PMID 25948104, 2015). "Although these results indicate that 18 F-FDG PET can be used to monitor tumor response to EGFR-TKIs, several limitations should be noted." (PMID 25888731, 2015). "On the other side, as we all know, Sp1 is responsible for up-regulation of housekeeping genes (VEGF, uPA, uPAR and EGFR), which participate in tumour cell angiogenesis and metastasis." (PMID 25639535, 2015). "Of these, [18F]16 and [18F]PEG6-IPQA were investigated in vivo and were shown to preferentially accumulate in high EGFR-expressing A431 tumor xenografts." (PMID 26690113, 2015). "In 1 out of 3 patients treated with panitumumab we found an acquired EGFR G465R ectodomain mutation after treatment with panitumumab and FOLFOX in post-treatment tumor material (patient 2)." (PMID 26059438, 2015). "Targeting the PI3K/AKT/mTOR pathway has been shown to increase anti-tumor activity of inhibiting EGFR." (PMID 25928246, 2015). "In clinical IBC tissues a clear correlation is demonstrated between p-EGFR staining in stromal and tumor cells in IBC highlighting the relevance of this cross-talk." (PMID 25887413, 2015).
tumor (continued). "Our findings are similar to the recently described transfer of the oncogenic epidermal growth factor receptor present on tumor-derived microparticles to endothelial cells or of the tissue factor present on macrophage-derived microparticles to platelets." (PMID 25720380, 2015). "Our results indicate that sulforaphane is a novel modulator of EGFR and is effective in inhibiting the tumor growth of EGFR-TKI-resistant NSCLC cells." (PMID 26036303, 2015). "In a preclinical study with tumor-bearing mice, 89Zr-cetuximab uptake was demonstrated in EGFR-positive tumors." (PMID 26309164, 2015). "Multiple mechanisms, such as unrestrained expression of EGFR, emergence of oncogenic mutants (KRAS, BRAF and PIK3CA) and inactivation of the PTEN tumour suppressor gene, underlie resistance to these drugs." (PMID 26113609, 2015). "PAR-1 expression was essential for tumor growth and invasion in mammary xenografts via thrombin-mediated interaction with EGFR- and ErbB or by the fibroblast-derived MMP-1-mediated Ca2+ pathway." (PMID 26573921, 2015). "Commonly, these studies measured the change in [18F]FLT tumor uptake prior to and after initiation of EGFR TKI therapy, to predict response to treatment." (PMID 25853010, 2015). "Recently ibrutinib has been reported to exhibit anti-tumor activities in EGFR mutant NSCLC and currently under phase I/II clinical trial for the previously treated NSCLC (NCT02321540)." (PMID 26375053, 2015). "EGFR tyrosine kinase inhibitors have a high affinity for mutant EGFR and block the downstream effects of activation resulting in inhibition of tumour growth and cell survival." (PMID 26101870, 2015). "The mechanism of action of EGFR inhibitors is the inhibition of tumor cell proliferation and induction of apoptosis." (PMID 26493267, 2015). "Although it is well known that PDAC is a Kras-driven cancer, data from in vitro and murine in vivo tumor models reveal the critical role of EGFR in pancreatic tumorigenesis and development." (PMID 25679210, 2015). "In general, obtaining PCR-based EGFR test results from outside laboratories requires 7–14 days after tumor sampling." (PMID 25651992, 2015). "While mutant EGFR did enhance the ability of MCF10CA1a cells to form tumours in nude BALB/c mice, it was unable to induce metastases after resection of the primary tumours or after intravenous injections in lung colonization experiments." (PMID 25969993, 2015). "Hyperactivation of EGFR-dependent signal transduction usually accompanies tumor development, and cancer patients with unbalanced activation of EGFR generally present with a more aggressive disease leading to unfavorable clinical prognosis." (PMID 26304749, 2015). "In a recent study, single-chain epidermal growth factor receptor antibody- (ScFvEGFR-) conjugated quantum dots (QDs) or magnetic iron oxide (IO) nanoparticles were used for tumor target imaging in vivo." (PMID 26579537, 2015). "Target binding in tumor dominates that in plasma, with greater affinities (IC50 of 0.025 μM for HER2, and 0.029 μM for EGFR) that effectively extract albumin-bound lapatinib from blood passing through the tumor." (PMID 26571496, 2015). "EGFR/CXCR4 coexpression was significantly associated with lymph node metastasis (P = 0.026), TNM stage (P = 0.048), and poor tumor differentiation (P = 0.004)." (PMID 25679210, 2015). "Disruption of CD151 or α3β1 integrin markedly impairs EGF/EGFR-evoked tumor cell motility and invasiveness." (PMID 26377974, 2015). "Signaling interactions between c-Met and EGFR pathways have been reported in various tumor types but are incompletely understood." (PMID 26000702, 2015). "In previous work, we showed that SP contributes to BC progression by modulating the activity of oncogenic receptors like HER2 and EGFR, thus influencing tumor responses to targeted therapies designed to inhibit these receptors." (PMID 26114632, 2015). "Elevated levels of the epidermal growth factor receptor (EGFR) have been noticed in several of tumour." (PMID 25977926, 2015).